AHR (aryl hydrocarbon receptor)
Diseases named in the same sentence as AHR in open-access papers (continued):
Sharing a sentence is not in itself a finding about the gene and the disease.
tumor (continued). "High level of AHR expression was noted in tumor cells co-expressing high level of HDAC8." (PMID 27283490, 2017). "With regards to cell proliferation, the corroboration of results from both in vivo specimens and in vitro analyses lend weight to the hypothesis that AHR may act as a tumour suppressor in PA." (PMID 28649092, 2017). "Because of the involvement of AhR-dependent genes in chemically induced carcinogenesis, suppression of this signaling pathway could prevent tumor formation and/or progression." (PMID 27167070, 2016). "Interestingly, these authors also showed that TDO-derived Kyn was able to inhibit anti-tumour effects and promote tumour-cell survival and dissemination through a direct effect on the AhR pathway." (PMID 27867514, 2016). "However, more recent work suggests that the AHR, which is expressed at aberrantly high levels and is chronically active in several cancers, plays an ongoing role in tumor progression by enhancing tumor invasion and migration." (PMID 26984638, 2016). "Notably, it has been shown that TDO-derived Kyn suppresses anti-tumour immune responses, thus promoting tumour-cell survival through activation of the AhR pathway." (PMID 27867514, 2016). "Knockdown of AHR reduced tumor cell growth and tumorsphere formation." (PMID 27509054, 2016). "In fact, it is possible that AhR could help modulate the balance between differentiation and pluripotency in normal and transformed tumor cells." (PMID 27243009, 2016). "This AhR-IL-6-STAT3 loop is associated with a poor prognosis in lung cancer, supporting the idea that IDO-mediated immunosuppression enables the immune escape of tumor cells." (PMID 26881062, 2015). "In parallel, another group provided evidence for a tumor cell autonomous effect of TDO expression in glioblastoma, promoting tumor progression through AhR activation by tryptophan catabolites, resulting in increased tumor cell survival and motility, and reduced anti-tumor immune responses." (PMID 25691885, 2015). "We first examined if single Aldh1a1 knockdown affected tumor formation in AhR expressing cells." (PMID 26242870, 2015). "In this regard, AhR can regulate tumor cell differentiation to a non-tumor phenotype." (PMID 25941627, 2015). "Thus, Aldh1a1 knockdown in sh-AhR cells (sh-AhR + sh-Aldh1a1) diminished their migration and invasion potentials and blocked tumor growth and metastasis to the lungs in immunocompetent AhR+/+ recipient mice." (PMID 26242870, 2015). "In addition, AhR also functions as a tumor suppressor for liver carcinogenesis by inhibiting cell proliferation through G0-G1 cell cycle arrest." (PMID 26264025, 2015). "Aryl hydrocarbon receptor repressor gene directly regulates ADM expression under normal physiologic conditions but may also play a role during the early stages of tumour genesis in the lung." (PMID 25623364, 2015). "Kynurenine has been shown to be an endogenous tumor-promoting ligand of the human AhR." (PMID 25060643, 2014). "Our data demonstrated that suppression of AhR by shRNA-AhR or exposure Biseugenol-induced Calpain-10-activity could reduce tumor growth or peritoneal dissemination in tumor tissues." (PMID 25226618, 2014). "Future studies designed to understand if and how AHR and Wnt signaling pathways intersect could shed light on mechanisms of tumor initiation, promotion, and progression while simultaneously providing potential targets for treatment." (PMID 25286307, 2014). "Importantly, previous studies have demonstrated that AhR participate in tumor initiation, promotion and progression." (PMID 25226618, 2014). "TDO-2-dependent production of KYN by gliomas might be a novel mechanism for suppressing anti-tumor immunity and supporting tumor growth through activation of the AhR." (PMID 25415278, 2014). "Activation of AhR regulates the activation of the mitogen-activated protein kinase or JunD, which is critically involved in contact inhibitor, inflammation, oncogenic events and tumor progression." (PMID 25226618, 2014).
tumor (continued). "In addition, known carcinogens such as cigarette smoking can increase AM expression through activation of aryl hydrocarbon receptor (AHR), and blockade of AM can decrease tobacco-induced tumour growth." (PMID 25475159, 2014). "Thus, AHR has a natural function as a tumor suppressor that is capable of downregulating CTNNB1 expression." (PMID 25286307, 2014). "The functional interaction between AhR and Cav-1 likely has an important contribution to the motility of mesenchymal cells, and emphasizes the relevance of both proteins in the migration of tumor cells." (PMID 25238970, 2014). "Thus, AHR in NB is likely to act as a tumor suppressor and promote tumor differentiation by downregulation of MYCN." (PMID 24586395, 2014). "Furthermore, AHRR, the negative regulator of AHR signaling, functions as a tumor suppressor in multiple human tumors." (PMID 23420531, 2013). "In addition, immunohistochemical staining suggested that vorinostat treatment induced cytoplasmic expression of AhR in MDA-MB-231 xenograft tumor tissues." (PMID 24058584, 2013). "Additionally, AHR plays a significant role in tumor promotion and progression by deregulation of cell–cell contact and inhibition of apoptosis." (PMID 23420531, 2013). "Recently, the AhR has been shown to act as a tumor suppressor in a mouse model of prostate cancer." (PMID 22815870, 2012). "The signals from AhR-resveratrol reaction might act as a mimic to the tumor-derived signals that induce the suppressive function of MDSCs." (PMID 22532866, 2012). "Thus, TDO exerts autocrine effects (on tumor cells) and paracrine effects (on immune cells) via kynurenine-mediated activation of the aryl hydrocarbon receptor." (PMID 23174128, 2012). "Together these data indicate that AhR has a distinct distribution pattern in tumor cells." (PMID 22295239, 2011). "Nonetheless, the activity spectrum of IO, which inhibits CDKs and has agonistic functions on the AhR, may be particularly favorable to target tumor cells." (PMID 20565777, 2010). "Results of the proliferation analysis in hNPCs are in contrast to previous findings obtained in human liver or neuroblastoma tumor cells that showed exogenous AhR activation by TCDD or other AhR ligands to inhibit cell proliferation and induce cell cycle arrest." (PMID 20570779, 2010). "In addition, a growing body of experimental evidence strongly suggests a role for the AHR in cell proliferation, differentiation, and liver and immune system homeostasis, as well as in tumor development." (PMID 19654925, 2009). "A case in point in this context may be the tumor suppressor gene Pten, which we verified by QPCR as being more highly bound by AHR in naive cells than in BaP- or TCDD-treated cells." (PMID 19654925, 2009). "In the tumours of advanced malignancy, the nuclear AHR was stabilised and constitutively active." (PMID 17242703, 2007). "Furthermore, indole-3-aldehyde mediates anti-tumor immunity by activating AhR in CD8+ T cells to promote IFN-γ production, and by promoting the ligand-dependent differentiation of CD4+ T cells into Th17 or Treg cells, ultimately enhancing the efficacy of immune checkpoint inhibitors." (PMID 41050671, 2025). "Moreover, AHR-high expression was associated with inflammatory response, IL-2 and IL-6 signalling, and tumour necrosis factor alpha (TNF-α) signalling via NF-κB in both ER+ and ER- tumours." (PMID 40646277, 2025). "Targeting AhR could prevent the downstream effects of kynurenine accumulation, including the expansion of Tregs and MDSCs, thereby restoring a more favorable immune environment for tumor destruction." (PMID 39997327, 2025). "Interestingly, PD-1 expression also decreased in healthy PBMCs after tumor co-culture, suggesting that AHR signaling may be involved in T cell exhaustion." (PMID 41357201, 2025). "Notably, AhR antagonist CH-223191 restores ferroptosis sensitivity of tumor cells." (PMID 41431173, 2025).
tumor (continued). "Notably, AHR knockout further enhanced anchorage-independent growth in BEAS-2B cells, with As3+ exposure increasing colony formation frequency by 20.13-fold compared to WT cells, further reinforcing AHR's tumor-suppressive role in As3+-induced malignant transformation." (PMID 40303305, 2025). "We next tested whether AhR expression in tumor cells could affect T cell activation." (PMID 40583248, 2025). "In addition, among the LNCaP xenograft tumours we collected, both TDO2 and AhR proteins were significantly upregulated in tumours that recurred after castration compared with normal tumours, and the mRNA levels of TDO2, AhR, and CYP1A1 were also significantly elevated." (PMID 40759641, 2025). "We next investigated whether the tumor‐suppressive effect of 3‐IAA is dependent on AhR." (PMID 40557796, 2025). "In addition, it can produce potent aryl hydrocarbon receptor (AhR) ligands, which may promote tumor development by modifying UV radiation carcinogenesis, altering cell cycle progression and inhibiting apoptosis." (PMID 40422666, 2025). "Notably, IDO2 exhibited a strong association with AhR expression and tumour cell density, with no observed correlation between AhR and either IDO1 or TDO2." (PMID 40471422, 2025). "Therefore, it is necessary to conduct metabolomics and single‐cell sequencing of different tumor types to understand how microbial metabolites affect the tumor microenvironment and how AhR signaling impacts different types of immune cells and host immune responses." (PMID 40103267, 2025). "Ablation of AhR (as seen in MOC1AhR KO cells) results in attenuated tumour growth within 1 week, leading to complete rejection within 2 weeks, along with an augmentation of activated T cells in tumour-draining lymph nodes (tdLNs) and enhanced T cell signalling within the tumour." (PMID 40994140, 2025). "In addition, AhR is expressed in both cancer cells and tumor-infiltrating immune cells and exerts a direct influence on their responses to the development and progression of cancer, thereby suggesting its involvement in multiple mechanisms that cancer cells utilize for growth and survival." (PMID 41155994, 2025). "In addition to its role in tumor immune evasion, AhR may also play a crucial role in the growth of tumor cells by controlling the cell cycle." (PMID 38434684, 2024). "Similarly, further studies of direct AhR inhibition by modulation of the microbiota could provide a novel means for boosting anti-tumor immunity." (PMID 38339226, 2024). "However, the role of AhR activation in stemness and chemoresistance can be tumor dependent." (PMID 38339226, 2024). "Also, blocking AhR reversed B. breve lw01-induced tumor inhibition and MCMs upregulation." (PMID 38773969, 2024). "Besides, we performed additional experiments to evaluate if antagonizing AhR could abolish B. breve lw01-mediated anti-inflammation and anti-tumor effects." (PMID 38773969, 2024). "AhR may contribute to the tumor–stroma interaction (through CYP1A1 and CYP1B1) in diffuse GC." (PMID 39200369, 2024). "In contrast, AhR may also be involved in facilitating tumor immune escape." (PMID 38518996, 2024). "Similarly, AhR signaling may be involved in the IL4I1-induced suppression of tumor cell ferroptosis." (PMID 39211039, 2024). "Generally, IDO1 signaling foster a tumor immunological microenvironment that is defective in recognizing and eradicating cancer cells by depleting Trp to generate Kyn, which in turn upregulates the immune‐tolerant cells levels within tumor tissues via activating AhR pathway." (PMID 38884220, 2024). "However, AhR is involved in carcinogenesis with both pro- and anti-tumor functions in different types of cancer, which possibly means that specific ligands may drive or suppress carcinogenesis." (PMID 38518996, 2024). "Furthermore, I3C acts as an AHR agonist and affects the tumor microenvironment." (PMID 39014007, 2024).
tumor (continued). "Furthermore, excess reactive oxygen species (ROS) from the TME may trigger the synthesis of antioxidant proteins by activating AhR, enabling tumor cell response to the TME." (PMID 38434684, 2024). "However, the difficult progress made with the combination of IDO inhibitors and immune checkpoint blockade therapies suggests that there may be other pathways of AHR activation that led to mechanisms of tolerance to IDO inhibitors in tumor cells." (PMID 38755125, 2024). "Furthermore, AHR’s role in modulating the immune response creates an immunosuppressive tumor environment, particularly through the regulation of T-cell differentiation and macrophage activation, further contributing to aggressive cancer phenotypes in AA patients." (PMID 39600743, 2024). "The mechanisms by which AHR shapes the tumor microenvironment are unclear, but it has been proposed that systemic and tumor-localized generation of endogenous AHR ligands heightened AHR expression/activity, which may establish a pro-inflammatory yet immune-suppressive tumor micro-environment." (PMID 38982523, 2024). "AhR activation has been found to promote the trans-differentiation of antigen-presenting cells (APCs), such as dendritic cells (DCs) and macrophages, toward a more tolerogenic or tumor-permissive phenotype, resulting in the generation of immune-suppressive regulatory T (Tregs) cells." (PMID 38807762, 2024). "Moreover, acting as a sensor also for GM metabolites, the AhR plays a role in microbe-mediated tumorigenesis through several mechanisms (e.g., the Wnt/β-catenin signalling pathway), promotes immune tolerance in tumour microenvironment, and tumour metastasis." (PMID 38799688, 2024). "However, in the presence of a large number of exogenous ligands or ligands produced by tumor cells, AhR may impede the clearance of tumors by the immune system and contribute to the onset of autoimmune diseases." (PMID 38883986, 2024). "As potent aryl hydrocarbon receptor (AhR) agonists, biochanin A and formononetin can transactivate the receptor and influence the ER signaling, and thus, in certain contexts, they might sustain tumor growth." (PMID 39765764, 2024). "Therefore, regulation of AHR activation via AHRR expression might indicate an important anti-oncogenic mechanism in primary tumours." (PMID 38361045, 2024). "Here we show that tumor cell-released kynurenine (Kyn) biases megakaryocytic–erythroid progenitor cell (MEP) differentiation into megakaryocytes in individuals with cancer by activating the aryl hydrocarbon receptor–Runt-related transcription factor 1 (AhR–RUNX1) axis." (PMID 37919525, 2023). "Thus, despite the finding that indole-producing Lactobacilli drastically increase tumor size by influencing immunity in the tumor microenvironment, these findings highlight the ligand-dependent activity of AhR and, at the same time, expand upon the therapeutic activity of 3-IAld." (PMID 36839828, 2023). "IDO2 may promote tumor immune suppression through the Trp-Kyn-AhR axis." (PMID 37876966, 2023). "Similarly, AHR has also been shown to play a crucial role in tumor cell proliferation and invasion." (PMID 37718440, 2023). "While extensive work has defined the negative impacts associated with the activation of AhR by ligands such as polycyclic aromatic hydrocarbons (PAHs) and dioxins, AhR activation can also promote desirable biological endpoints such as tumor suppression and immunomodulation." (PMID 37106727, 2023). "Thus, interruption of the tumor suppressive-like activity of AHR, followed by the intensified TGFβ signaling, Nrf2 signaling and others, may be one of the key mechanisms of As3+-induced carcinogenesis." (PMID 37151890, 2023).
tumor (continued). "Moreover, AhR is able to increase epiregulin expression and gene transcription, which could play an important role in tumor promotion." (PMID 37447165, 2023). "Huang and colleagues show that in tumor-bearing individuals, increased circulating kynurenine results in megakaryocyte differentiation from megakaryocytic–erythroid progenitor cells by activating the aryl hydrocarbon receptor, resulting in increased expression of RUNX1." (PMID 37919525, 2023). "However, the new data reveal that in ccRCC tumours, competition for HIF-1β/ARNT results in a reciprocal relationship between HIF and AHR and constitutive activation of HIF is associated with suppression of the AHR pathway." (PMID 36725335, 2023). "Therefore, AhR is important for tumorigenesis, but how it affects tumor progression remains unclear." (PMID 37056388, 2023). "Furthermore, in the MB49 orthotopic tumor model, we found that either inhibition of AhR, IDO1 or SLC7A5 could achieve synergistic effect with cisplatin." (PMID 37670034, 2023). "However, in a tumor microenvironment AHR activation could lead to enhanced inflammatory signaling, which would likely be pro-survival." (PMID 37755265, 2023). "It is of note that potent carcinogens, such as B [a]P and 5-methylchrysene, may combine multiple types of toxic activities, including genotoxicity, AhR-mediated activity and tumor promotion activities (see section 9), and they occur at relatively high concentrations in polluted air." (PMID 37696458, 2023). "Surprisingly, although Ido1, Ido2 and Tdo2 were barely expressed in MEPs, a high level of Kyn was found in the MEPs of tumor-bearing mice and a very low Kyn level was present in the MEPs of tumor-free mice, suggesting that MEPs from tumor-bearing hosts might use exogenous Kyn to activate AhR." (PMID 37919525, 2023). "The AhR has emerged as a potential drug target for multiple diseases including cancer; however, there are still some conflicting reports regarding the pro-oncogenic or tumor suppressor-like activity of the receptor and its ligands and this is particularly true for breast cancer." (PMID 38651159, 2023). "Moreover, AhR deficiency inhibited, rather than enhanced, tumor formation and tumor-derived organoids in Apc-deficient cells both in vivo and in vitro by activating Wnt/β-catenin signaling and TCF4/LEF1-dependent transcription." (PMID 37781044, 2023). "Recently, Sadik and co-workers proposed that IL4I1 expression may also underlie the resistance of patients against IDO1 inhibition, with activation of the AhR presented as their common mechanism of immune response blockade and promotion of tumor cell malignancy." (PMID 36765849, 2023). "Thus, effects of PAHs on HIF-1a-driven angiogenesis in tumor cells could be regulated not only by their AhR activity but they could be directed also by a pattern of their metabolites being formed in target cells." (PMID 37696458, 2023). "Besides the presence of AhR at the plasma membrane, previous works have also pointed to the existence of a pool of AhR located in mitochondria, with possible consequences in terms of the metabolic reprogramming involved in tumor development." (PMID 37696458, 2023). "Additionally, Ido1 expression in tumor tissues promotes Treg differentiation/activation by catabolizing tryptophan to produce kynurenine and ultimately activating aryl hydrocarbon receptors (AhR)." (PMID 36010693, 2022). "Inhibiting AhR mitigated CD155 expression on TAMs could reverse tumor immunosuppression." (PMID 35681736, 2022). "In addition, AhR signaling mediates tumor immunosuppression by promoting CD155 expression on TAMs." (PMID 35681736, 2022).